MIR9-3 (microRNA 9-3)
Synonyms: hsa-mir-9-3; MIRN9-3; miRNA9-3; mir-9-3
Gene: MicroRNA gene on chromosome 15 (89,368,017 to 89,368,106, forward strand). Ensembl gene ENSG00000284329.
Pathways (Reactome):
Cell-Cell communication: Regulation of CDH1 mRNA translation by microRNAs
Gene Ontology:
Biological process: miRNA-mediated post-transcriptional gene silencing
Cellular component: RISC complex
Homologues: Orthologues: chimpanzee MIR9-3 (99% identical), dog MIR9-3 (99% identical), guinea pig MIR9-3 (99% identical), macaque mml-mir-9-3 (99% identical), mouse Mir9-3 (99% identical), pig ssc-mir-9-3 (99% identical). Paralogues in human: MIR9-1 (77% identical), MIR9-2 (77% identical).
Diseases named in the same sentence as MIR9-3 in open-access papers:
MIR9-3 is named in the same sentence as 10 diseases in open-access papers, as found by Europe PMC text mining. Sharing a sentence is not in itself a finding about the gene and the disease. The quoted sentences say what the papers report.
insomnia (1 paper, 2023). A sleep disorder characterized by difficulty in falling asleep and/or remaining asleep. "This combination of features suggests possible and likely enhancer functions for the respective SNPs regarding MIR9-3, providing a plausible functional basis for their associated trait, insomnia." (PMID 37679839, 2023).
ovarian carcinoma (1 paper, 2015). A malignant neoplasm originating from the surface ovarian epithelium. "MIR-93 mRNA expression was significantly lower in ovarian carcinomas and borderline tumors than in normal ovarian tissues (p < 0.05), and was lower in metastatic omentum than in relative primary ovarian carcinomas (p < 0.05)." (PMID 25649143, 2015). "Our results show that MIR93 mRNA expression was significantly lower in ovarian carcinomas, borderline tumors, and metastatic omentum, and was negatively associated with differentiation and FIGO staging in ovarian carcinoma." (PMID 25649143, 2015). "MIR-93 mRNA expression in normal ovarian tissue, benign tumors, borderline tumors, primary ovarian carcinomas, and metastatic omentum was quantified." (PMID 25649143, 2015).
tumor (4 papers, 2017 to 2024). "We identified MIR182, MIR183, MIR371, MIR373, MIR512-1, MIR512-2, MIR515-1, and MIR520e exhibiting high expression and MIR216b, MIR887, MIR9-2, and MIR9-3 exhibiting low expression in NANOG H/L tumours." (PMID 38693576, 2024). "The MIR9-2 promoter was methylated in 5 out of 10 NBTs and 58 out of 101 tumours (p = 0.744) and MIR9-3 promoter in 4 out of 10 NBT and in 71 out of 101 tumours (p = 0.075)." (PMID 28345661, 2017). "MIR-93 promotes tumor angiogenesis by reducing the expression of EPLIN." (PMID 34616746, 2021).
MIR9-3 also shares sentences with these, for which no sentence is quoted: benign tumors (1 paper); breast carcinoma (1); metastatic tumors (1); mucinous adenocarcinoma (1); ovarian tumors (1); pancreatic adenocarcinoma (1); prostate carcinoma (1).